RAG2 (recombination activating 2)
Description:
Core component of the RAG complex, a multiprotein complex that mediates the DNA cleavage phase during V(D)J recombination. V(D)J recombination assembles a diverse repertoire of immunoglobulin and T-cell receptor genes in developing B and T-lymphocytes through rearrangement of different V (variable), in some cases D (diversity), and J (joining) gene segments. DNA cleavage by the RAG complex occurs in 2 steps: a first nick is introduced in the top strand immediately upstream of the heptamer, generating a 3'-hydroxyl group that can attack the phosphodiester bond on the opposite strand in a direct transesterification reaction, thereby creating 4 DNA ends: 2 hairpin coding ends and 2 blunt, 5'-phosphorylated ends. The chromatin structure plays an essential role in the V(D)J recombination reactions and the presence of histone H3 trimethylated at 'Lys-4' (H3K4me3) stimulates both the nicking and haipinning steps. The RAG complex also plays a role in pre-B cell allelic exclusion, a process leading to expression of a single immunoglobulin heavy chain allele to enforce clonality and monospecific recognition by the B-cell antigen receptor (BCR) expressed on individual B-lymphocytes. The introduction of DNA breaks by the RAG complex on one immunoglobulin allele induces ATM-dependent repositioning of the other allele to pericentromeric heterochromatin, preventing accessibility to the RAG complex and recombination of the second allele. In the RAG complex, RAG2 is not the catalytic component but is required for all known catalytic activities mediated by RAG1. It probably acts as a sensor of chromatin state that recruits the RAG complex to H3K4me3 (By similarity).
Synonyms: RAG-2
Tractability: PROTAC: ubiquitination databases record sites on it.
Gene: Protein-coding gene on chromosome 11 (36,575,574 to 36,598,279, reverse strand). Ensembl gene ENSG00000175097.
Subcellular location: Nucleus
Subcellular location (Human Protein Atlas): Nucleoplasm
Pathways (Reactome):
Immune System: Interleukin-7 signaling
Signal Transduction: MAPK6/MAPK4 signaling
Gene Ontology:
Molecular function: chromatin binding; histone H3K4me3 reader activity; phosphatidylinositol binding; phosphatidylinositol-3,4,5-trisphosphate binding; phosphatidylinositol-3,4-bisphosphate binding; phosphatidylinositol-3,5-bisphosphate binding; phosphatidylinositol-4,5-bisphosphate binding; sequence-specific DNA binding; zinc ion binding; DNA binding
Biological process: B cell differentiation; pre-B cell allelic exclusion; T cell differentiation in thymus; V(D)J recombination; chromatin organization; DNA recombination; mature B cell differentiation involved in immune response; negative regulation of T cell differentiation in thymus
Cellular component: DNA recombinase complex; nucleoplasm; nucleus
Genetic constraint (gnomAD): Loss-of-function variants: 16 observed, 33.16 expected, observed/expected ratio (o/e) 0.48, 90% interval 0.33 to 0.73. The upper end of that interval is the gene's LOEUF score, 0.73, which puts it in group 3 of 6, group 1 being the genes least tolerant of losing a copy. Missense variants: 617 observed, 657.98 expected, observed/expected ratio (o/e) 0.94, 90% interval 0.88 to 1. Synonymous variants: 199 observed, 228.23 expected, observed/expected ratio (o/e) 0.87, 90% interval 0.78 to 0.98.
Gene-disease validity (ClinGen):
ClinGen rates the evidence that RAG2 causes each of these diseases.
recombinase activating gene 2 deficiency (autosomal recessive): Definitive. A severe combined immunodeficiency that is the result of a mutation on Chromosome 6 RAG2 gene involving genetic rearrangement of both the T- and B-lymphocyte receptor genes.
Homologues: Orthologues: chimpanzee RAG2 (99% identical), macaque RAG2 (99% identical), rabbit RAG2 (92% identical), pig RAG2 (91% identical), guinea pig RAG2 (90% identical), rat Rag2 (89% identical), dog RAG2 (89% identical), mouse Rag2 (88% identical), tropical clawed frog rag2 (60% identical), zebrafish rag2 (52% identical).
Diseases named in the same sentence as RAG2 in open-access papers:
RAG2 is named in the same sentence as 214 diseases in open-access papers, as found by Europe PMC text mining. Sharing a sentence is not in itself a finding about the gene and the disease. The quoted sentences say what the papers report.
colitis (84 papers, 2007 to 2026). Inflammation of the colon. "After adoptively transferring naïve CD4+ T cells from syngeneic mice to recombinase activating gene-2-deficient (Rag2-/-) mice, the mice showing the colitis symptom in the form of loose stool in 4-6 weeks were randomly divided into two groups." (PMID 35990633, 2022). "Blocking T1IFN signaling during colitis resulted in exaggeration of colitis in both wild-type and Rag2-deficient mice." (PMID 36268010, 2022). "Consistent with WT mice, neutralizing T1IFN signaling resulted in a more sever colitis histology in Rag2-deficient mice." (PMID 36268010, 2022). "Following the adoptive transfer of naïve CD4+ CD25- CD62L+ CD44low T cells into Rag2-/- mice, colitis ensued by day 30, with mice suffering weight loss and diarrhea." (PMID 35660024, 2022). "In an experimental mouse model of colitis induced by α-CD40 Ab injection into Rag2-deficient mice it was shown that ILC3s contribute to the pathology by IL-23-driven release of IFN-γ13,15,16." (PMID 34341503, 2021). "In recombination-activating gene 2 (Rag2)-deficient mice treated with α-CD40 antibodies (Abs) to elicit colitis, the release of IL-23 by myeloid cells activates colonic ILC3s to switch to pro-inflammatory IFN-γ production, thereby promoting the disease." (PMID 34341503, 2021). "We have demonstrated that Tbx21-/- mice on a BALB/c Rag2-/- background are more susceptible to H. thyphlonius-driven colitis in comparison to conventional BALB/c background Rag2-/- mice pointing to a protective role of T-bet." (PMID 34795671, 2021). "In immune-deficient RAG2 mice, ILC3s were shown to play an important role in the development of Hh-induced colitis." (PMID 33255175, 2020). "While RAG-deficient (RAG2−/−) recipients of CD4+ T cells suffered from severe colitis with weight loss and high-grade intestinal inflammation, co-transfer of Keap-deficient CD11b+Gr-1+ cells markedly reduced loss of weight and intestinal inflammation." (PMID 30034396, 2018). "Accordingly, transfer of Was-deficient CD4+ T cells into Rag2-deficient mice is sufficient to induce colitis." (PMID 30410494, 2018). "Body weight loss resulting from colitis was observed in Rag2-/- mice that received a transfer of naïve CD4+T cells." (PMID 24058613, 2013). "We examined the contribution of IL-7R on inflammation and disease development in two models of experimental colitis: Helicobacter bilis (Hb)-induced colitis in immune-sufficient Mdr1a−/− mice and in T- and B-cell-deficient Rag2−/− mice." (PMID 23057802, 2012). "We used Helicobacter bilis (Hb) infection to induce colitis in T-cell-sufficient (multiple drug resistance 1a null; Mdr1a−/−) mice, and T- and B-cell-deficient (recombination activating gene 2; Rag2−/−) mice." (PMID 23057802, 2012). "Hepcidin expression was evaluated in two types of intestinal inflammation caused by innate immune activation—dextran sulfate sodium (DSS)-induced colitis in wild-type mice and the spontaneous colitis occurring in T-bet/Rag2-deficient (TRUC) mice." (PMID 22675442, 2012). "RAG-2-/- mice deficient in T and B cells also developed severe ongoing colitis in response to 3 cycles of DSS, but showed marked differences vs. wild type mice in stool TNF and TNF-RII in response to DSS exposure." (PMID 18331642, 2008). "Experimentally, 129/SvEv Rag-2-deficient mice have been shown to develop colitis and colonic cancer in the presence of Helicobacter." (PMID 17498313, 2007). "Nevertheless, when transferred together with CD45RBhigh pathogenic T cells into Rag2–/– mice, splenic Setd2-deficient Treg cells had a reduced capacity to suppress colitis compared to control Treg cells in vivo, as indicated by the greater body weight loss and shortened colons of recipient mice." (PMID 36463230, 2022).
colitis (continued). "To investigate the role of T1IFN signaling in ILC2s, we assessed mice treated with anti-T1IFN receptor and observed reduced amphiregulin (AREG) production in ILC2s and exaggeration of colitis in wild-type (WT) and Rag2-deficient mice, which was rescued by supplementation with AREG." (PMID 36268010, 2022). "To test whether CD4 T cells were similarly affected by Arl4d deficiency, we used the model of transfer colitis by the adoptive transfer of CD25negCD62Lhigh CD4 T cells from either Arl4d+/+ or Arl4d−/− mice into Rag2-deficient mice." (PMID 36078047, 2022). "In order to determine whether reduced epithelial Na+/H+ exchange altered susceptibility to T cell-mediated colitis, we adoptively transferred Rag2-/- and DKO mice with naïve T cells." (PMID 27050757, 2016). "In attempts to confirm this, we have undertaken gender mis-matched bone marrow (BM) transplants from male Swiss Webster (SWR) mice to B and T cell-deficient female Rag2 KO mice which, 4 weeks later, were given 5% dextran sodium sulphate in drinking water to induce acute colitis." (PMID 22022515, 2011). "In addition, when Rgs1−/− and wild-type T cells are transferred in the inflammatory colitis model in Rag2-deficient mice, wild-type mice were more susceptible to colitis, presumably through RGS1 repressing T-cell egress from the gut14 associating RGS1 in having a key role in leukocyte accumulation." (PMID 25782711, 2015). "In addition, our colitis models provided the opportunity to assess the cell types and functions affected by blocking IL-7Rα in mice where intestinal immunopathology is associated with T cells (in Mdr1a−/− mice), and innate immune cells (in Rag2−/− mice)." (PMID 23057802, 2012). "Rag2-/- hosts that received Cars2+/- versus WT CD4+ T cells exhibited severer body weight loss and histological colitis." (PMID 40303402, 2025). "An interesting example of this is a recent study using a colitis model induced by transferring naïve CD4+ T cells into Rag2-/- mice." (PMID 38719901, 2024). "Transfer of naive CD4+ T cells into immunodeficient Rag2-knockout (Rag2−/−) mice induces colitis and small bowel inflammation." (PMID 37301920, 2023). "Next, we sought to further analyze CD90 expression dynamics in a model of dysbiosis-driven spontaneous colitis in Rag2-/- mice." (PMID 37114052, 2023). "The Mettl3-deficient naïve T-cells were defective in adoptive transfer colitis experiments using Rag2-knockout mice, which cannot produce mature T- and B-cells, and were unable to promote the development of colitis, in contrast to wild-type T-cells." (PMID 37509095, 2023). "On the other hand, for T-cell-transfer-mediated colitis, Rag1 -/- and Rag2 -/- are often used interchangeably due to their phenotypic similarities." (PMID 36672648, 2023). "We have previously shown that spontaneous colitis in Tbx21-/- x Rag2-/- ulcerative colitis (TRUC) mice is partially driven by IL-17A-producing CD90+ ILC." (PMID 37114052, 2023). "On the other hand, in ILCs-related colitis models such as CD40 colitis, IL-10 colitis, T-bet (-/-) Rag2 (-/-) ulcerative colitis (TRUC), GPR183 is one of the pathogenic mechanisms." (PMID 37720208, 2023). "Naïve CD4+ T lymphocytes are known to induce severe colitis when transferred to Rag2 knockout (KO) mice." (PMID 35707543, 2022). "To determine if ILC2s acted downstream of IL-33 signaling during protection from amebic colitis, we adoptively transferred ILC2s into RAG2−/−γc−/− mice." (PMID 34400793, 2022). "We further identified that the same subset induces the most severe colitis when transferred to Rag2 KO mice, demonstrating its potential role in inflammation in vivo." (PMID 35707543, 2022). "Blocking of IFNAR1 reduced AREG-expressing ILC2s in WT and Rag2-deficient mice, which have been reported to play critical roles in DSS-induced colitis." (PMID 36268010, 2022).
colitis (continued). "We showed that Setd2-deficient Treg cells had increased fate conversion in CD45RBhighT cell-induced colitis and during homeostatic expansion in Rag2–/– mice." (PMID 36463230, 2022). "To test the TH polarization capacity and pathogenic function of Relb-deficient T cells in vivo, we next used a T-cell-transfer model of colitis, in which naïve Tconv cells are transferred to immunodeficient Rag2–/– recipients." (PMID 34608221, 2021). "For these analyses, TRnUC mice on a BALB/c background were chosen because Rag2-/-xTbx21-/- mice on this background appear to be more prone to colitis than C57BL/6 background Rag2-/-xTbx21-/- mice." (PMID 33603753, 2020). "In this experiment, ZFP36L2 iTregs or mock iTregs were adoptively co-injected with naive CD4+ T cells into RAG2−/− mice, and the development of colitis was evaluated by histological analyses and by its effect on the mice weight." (PMID 32655569, 2020). "The role of Gab2/3 in macrophages during colitis development was next assessed, where 1 × 106 LPS-polarized BMDMs from Gab2/3−/− or WT were adoptively transferred into Rag2−/− mice first, and then sorted naïve WT CD4+ T-cells were transferred 24 h later." (PMID 30936879, 2019). "T-bet deficiency in the innate immune system has been previously linked with aberrant IL-17 production by ILCs, as seen in the TRUC model, a colony of T-bet−/− x RAG2−/− that develops microbiota-dependent colitis in response to Helicobacter typhlonius." (PMID 30356098, 2019). "As part of the phylum Deferribacteres, Mucispirillum has been shown to be associated with both inflammatory markers and active colitis in a T-bet-/- Rag2-/- mouse model and was even associated with Citrobacter rodentium infection." (PMID 30873131, 2019). "In our study, we observed less severe colitis in Rag2 k.o. mice transferred with CD45RBhighIL-21R−/− CD4+ T cells compared with mice transferred with CD45RBhighIL-21R+/+ CD4+ T cells." (PMID 29849593, 2018). "To better understand how the Hiccs locus regulates colitis, we performed transcriptomic analysis of colon tissue from 129.Rag2−/− and 129.HiccsB6." (PMID 30228258, 2018). "In contrast, H. polygyrus pre-infection in the RAG2-/- T cell transfer colitis model seems to induce IL-6 and CXCL1 in the colon in the same manner as in the DSS model." (PMID 28938014, 2017). "We therefore, considered the possibility that the difference in colitis between Rag‐2−/− and TL−/−Rag‐2−/− mice was due to an increase in the effector functions of NK1.1+NKp46+ cells in TL−/−Rag‐2−/− mice." (PMID 28474503, 2017). "To confirm the role of CD4+ T cells in the MAP-mediated exacerbation of the DSS-induced colitis, we next treated RAG2−/− mice, which lack T and B cells with DSS and subsequently challenged them with MAP." (PMID 28361039, 2017). "Following adoptive transfer of naïve CD4+CD45RBhi T cells, Rag2-/- mice typically develop mild to moderate colitis within 6–8 weeks." (PMID 27050757, 2016). "Similar effects of GM-CSF blockade were also observed in bacteria-induced innate colitis following Helicobacter hepaticus infection of 129SvEv Rag2-/- mice supporting a pivotal role for this cytokine in both T cell dependent and innate colitis." (PMID 26780670, 2016). "Tbx21-/-Rag2-/- ulcerative colitis (TRUC) mice spontaneously develop severe colitis with striking similarities to some aspects of human UC." (PMID 25917784, 2015). "In contrast, Gr1+ cells, representing infiltrating Ly6Chi Gr1int monocytes and Ly6Cint Gr1hi neutrophils, were readily detected in Trem1+/+ x Rag2+/+ mice and Trem1−/− x Rag2−/− mice at 12–13 days post colitis induction." (PMID 24453980, 2014). "The reduced expression of pro-inflammatory mediators in the entire colonic LP in Trem1−/− x Rag2−/− mice at the late stage of colitis induction certainly also mirrors the decreased cellular infiltration." (PMID 24453980, 2014).
colitis (continued). "Rag-2 deficient mice were fed fish oil (FO) enriched in omega-3 fatty acids i.e. EPA and DHA or control diet for 4 weeks before colitis induction by adoptive transfer of naïve T cells and maintained in the same diet for 4 additional weeks." (PMID 23725086, 2013). "The defective suppression activity of TRAF6-deficient Tregs was confirmed through the failure to suppress colitis in Rag2-/- mice by the co-transfer of naïve T cells and Tregs." (PMID 24058613, 2013). "Our studies using Mdr1a−/− and Rag2−/− mice strongly suggest that cells other than CD4+ T cells are important in bacterial-induced colitis." (PMID 23057802, 2012). "Accordingly, we evaluated another model of intestinal inflammation caused by innate immune activation – spontaneous colitis occurring in TRUC mice, which have a combined deficiency of Rag2 and T-bet." (PMID 22675442, 2012). "Nonetheless, these apparently potent Gαi2−/− Treg, paradoxically, were only partially protective against colitis in the RAG2−/− transfer model." (PMID 21966415, 2011). "We decided to use the DSS colitis model to avoid confounding effects of immunodeficiency on beta‐amyloid pathology (SCID/RAG2‐/‐) and because IL‐10 crossed with beta‐amyloid overexpressing mice have reduced deposition, showing that IL‐10 plays a role in beta‐amyloid pathology." (PMID 40457749, 2025). "First, to address whether PRR deficiency enhances the proliferation and pathogenicity of Th1 and Th17 cells in colitis, we transferred naive CD4 T cells from PRRcKO mice into RAG2-deficient mice." (PMID 41451235, 2025). "Using CD4CRE CREBfl/fl mice, they showed that these cells prevented colitis in a Rag2-/- model; however, their model had the disadvantage that the CD4 cells of these mice expressed lower amounts of IL-2, which could have hampered iTreg induction." (PMID 40777015, 2025). "It was previously reported that the transfer of naïve T cells without Tregs into Rag1−/− or Rag2−/− mice causes spontaneous colitis in an IL-23-dependent manner, whereas cotransfer with Tregs prevents the development of colitis." (PMID 39379604, 2024). "The enhanced regulatory function of Ctsw−/− pTreg cells was further evaluated in a T cell cotransfer colitis model.WT CD4+CD25−CD45RBhi cells were transferred into Rag2−/− mice, together with either WT or Ctsw−/− in vitro–differentiated Foxp3+ (GFP) pTreg cells at a ratio of 10:1." (PMID 37436991, 2023). "Additionally, β7-integrin-expressing monocyte infiltration exacerbates DSS-induced colitis in RAG2 mice, which lack mature lymphoid cells, emphasizing the role of monocytes, not lymphocytes, in colitis development in these models." (PMID 36389795, 2022). "However, we detected a minimal number of eosinophils and mast cells in colitic Rag2-deficient mice, in which blocking T1IFN worsened colitis." (PMID 36268010, 2022). "To find out if the reduced Treg cells in the “T + KOTreg” group was due to fate conversion, we transferred Thy1.1+CD45RBhigh pathogenic T cells and Thy1.2+Ctrl Treg or Thy1.2+KO Treg cells to Rag2–/– mice, which were sacrificed for analysis when the mice developed colitis." (PMID 36463230, 2022). "The role of TH1 and TH17 cells in inflammatory disease is reflected by the induction of colitis upon adoptive transfer of naïve CD4+ T cells into Rag2–/– mice, which is marked by a wasting phenotype, inflamed colon, splenomegaly, and a TH1/TH17 hybrid‐driven inflammatory response." (PMID 35092032, 2022). "Thus, among the four MP subpopulations, the CD127hi Sca1hi subset induces the most severe colitis when transferred to Rag2 KO mice." (PMID 35707543, 2022). "In contrast to studies suggesting that ILC1 promote colitis, we have reported previously that T-bet expression can also protect from colitis, as Rag2-/- mice with germline deletion of Tbx21 can develop spontaneous colitis if Helicobacter thyphlonius is present in the gut." (PMID 34795671, 2021).